IGHA1 (immunoglobulin heavy constant alpha 1)
Description:
Constant region of immunoglobulin heavy chains. Immunoglobulins, also known as antibodies, are membrane-bound or secreted glycoproteins produced by B lymphocytes. In the recognition phase of humoral immunity, the membrane-bound immunoglobulins serve as receptors which, upon binding of a specific antigen, trigger the clonal expansion and differentiation of B lymphocytes into immunoglobulins-secreting plasma cells. Secreted immunoglobulins mediate the effector phase of humoral immunity, which results in the elimination of bound antigens. The antigen binding site is formed by the variable domain of one heavy chain, together with that of its associated light chain. Thus, each immunoglobulin has two antigen binding sites with remarkable affinity for a particular antigen. The variable domains are assembled by a process called V-(D)-J rearrangement and can then be subjected to somatic hypermutations which, after exposure to antigen and selection, allow affinity maturation for a particular antigen. Ig alpha is the major immunoglobulin class in body secretions.
Synonyms: AL928768.3; IgA1
Tractability: Antibody: its Gene Ontology location is reachable by antibodies, with high confidence; UniProt places it where antibodies can reach, with medium confidence; UniProt predicts a signal peptide or a membrane-spanning region. PROTAC: ubiquitination databases record sites on it.
Gene: Immunoglobulin constant (C) gene on chromosome 14 (105,703,995 to 105,708,665, reverse strand). Ensembl gene ENSG00000211895.
Subcellular location: Secreted (Isoform 1); Cell membrane (Isoform 2)
Pathways (Reactome):
Hemostasis: Cell surface interactions at the vascular wall
Vesicle-mediated transport: Scavenging of heme from plasma
Gene Ontology:
Molecular function: immunoglobulin receptor binding; antigen binding
Biological process: antibacterial humoral response; glomerular filtration; positive regulation of respiratory burst; adaptive immune response; B cell receptor signaling pathway; complement activation, classical pathway; immune response
Cellular component: blood microparticle; extracellular exosome; extracellular region; monomeric IgA immunoglobulin complex; secretory dimeric IgA immunoglobulin complex; secretory IgA immunoglobulin complex; IgA immunoglobulin complex; IgG immunoglobulin complex; immunoglobulin complex, circulating; plasma membrane
Homologues: Orthologues: mouse Igha (60% identical). Paralogues in human: IGHA2 (91% identical), IGHM (31% identical), IGHG1 (29% identical), IGHG3 (29% identical), IGHG2 (28% identical), IGHG4 (28% identical), IGHE (28% identical), IGHD (25% identical), IGLL1 (11% identical), IGLL5 (11% identical), IGLC2 (9% identical), IGLC3 (9% identical), and 65 more.
Diseases named in the same sentence as IGHA1 in open-access papers:
IGHA1 is named in the same sentence as 144 diseases in open-access papers, as found by Europe PMC text mining. Sharing a sentence is not in itself a finding about the gene and the disease. The quoted sentences say what the papers report.
COVID-19 (36 papers, 2020 to 2025). A disease caused by infection with severe acute respiratory syndrome coronavirus 2. "IGHA1, which is associated with an antibody immune response, was significantly up-regulated in survivors, suggesting an increased immune response in COVID-19 patients." (PMID 37949875, 2023). "Immunoglobulin-encoding genes were markedly over-expressed in COVID-19 compared to HLTY and INFL, and peaked in OXY1/TUBE EARLY (“hill” pattern, e.g. IGHM, IGHA1, IGHG1, JCHAIN)." (PMID 34135895, 2021). "There was also an increase in the mean CDRH3 length of the BCRs in the COVID-19 patients, that was most pronounced in the IGHA1, IGHA2, and IGHG1 isotype subclasses." (PMID 33384691, 2020). "The significantly increased usage of IGHA1 observed in the COVID-19 patients is in line with mucosal responses, where the longer hinge in IGHA1 compared to IGHA2 may offer advantages in antigen recognition by allowing higher avidity bivalent interactions with distantly spaced antigens." (PMID 33384691, 2020). "As a whole, COVID-19 patient PC GSVA scores were significantly correlated with IGHG3 and IGHA1 Ig heavy chain isotypes." (PMID 36189236, 2022). "Intriguingly, differentially expressed genes shared between non-survivors of COVID-19 and HAP/CAP included genes associated with both innate immunity (e.g., BPIFA1) and adaptative immunity (e.g., IGHA1)." (PMID 37949875, 2023). "Specifically, signatures of plasma cells (IGHG3, IGKC, IGHM, JCHAIN, IGHG2, IGKV4-1, IGLV3-1, IGHA1), activated fibroblasts (COL1A1, COL1A2, COL3A1), inflammatory cytokines (CXCL9, CCL18) and complement factors (C1QB, C1QC) dominated the DE genes for the COVID-19 lung sections." (PMID 37858234, 2023).
autoimmune disease (23 papers, 2011 to 2026). A disorder resulting from loss of function or tissue destruction of an organ or multiple organs, arising from humoral or cellular immune responses of the individual to their own tissue constituents. "Interestingly, several studies have reported that a combination of biomarkers, including IGKC and IGHA1, has good prognostic value in clear cell renal cell carcinoma and autoimmune diseases." (PMID 35646951, 2022).
myeloma (15 papers, 2011 to 2025). "C1 IGHA1+ Myeloma cells were mainly distributed in the middle stage, namely State 2; C2 IGHG1+ Myeloma cells and C3 IGHG4+ Myeloma cells were mainly distributed in the final stage of the trajectory, that is, State3." (PMID 40406148, 2025). "The regulatory activities of the four myeloma cell subpopulations varied in different regulatory modules, with some degree of regulatory activity of C0 IGLC3+ Myeloma cells in the M1 and M4 regulatory modules, C0 IGLC3+ Myeloma cells and C1 IGHA1+ Myeloma cells in the M2 regulatory module." (PMID 40406148, 2025). "The results showed that C0 IGLC3+ myeloma cells had the highest differentiation potential, indicating that C0 IGLC3+ myeloma cells had the strongest proliferation ability and were naive tumor cells, followed by C1 IGHA1+ myeloma cells, C2 IGHG1+ myeloma cells, and C3 IGHG4+ myeloma cells." (PMID 40406148, 2025). "C1 IGHA1+ aerobic respiration, respiratory electron transport chain, ATP synthesis linked electron transport, mitochondrial ATP synthesis coupled electron transport, oxidative phosphorylation, and other pathways were enriched in C2 IGHG1+ in myeloma cells." (PMID 40406148, 2025). "Interestingly, myeloma patients with IgA depletion had a significant downregulation of immunoglobulin heavy constant alpha 1 and 2 (IGHA1 and IGHA2) when compared to patients with normal and elevated levels of IgA." (PMID 35800053, 2022). "The results showed that KLF6, NR3C1, IRF7 and YY1 were all actively regulated in C0 IGLC3+ Myeloma Cells, C1 IGHA1+ Myeloma Cells, and JUN was actively regulated in C0 IGLC3+Myeloma Cells, C1 IGHA1+ Myeloma Cells and C3 IGHG4+ Myeloma Cells." (PMID 40406148, 2025). "We classified 1501 plasma cells in MM into four distinct cell subsets, C1 IGHA1+ Myeloma cells, C2 IGHG1+ Myeloma cells, and C3 IGHG4+ Myeloma cells, in order to better understand the characteristics of plasma cells in MM." (PMID 40406148, 2025). "We investigated the differentiation trajectories of malignant plasma cells and identified four major myeloma subpopulations: C0 IGLC3+, C1 IGHA1+, C2 IGHG1+, and C3 IGHG4+ myeloma cells." (PMID 40406148, 2025).
breast cancer (12 papers, 2013 to 2025). A primary or metastatic malignant neoplasm involving the breast. "Prior studies link FASN, GNAS, and IGHA1 to breast cancer progression and suggest prognostic potential." (PMID 41263940, 2025). "IGHA1 and IGHA2 mRNA levels are highly correlated and are associated with improved prognosis with a higher immune activity in breast cancer." (PMID 35281270, 2022). "IGHA1 was up-regulated and reported as an unfavorable biomarker in renal cell carcinoma and prostate cancer, while reported as a favorable biomarker in breast cancer." (PMID 37503341, 2023). "A total of 88 candidate genes related to breast cancer prognosis were screened, of which CD48, SLAMF7, SLAMF1, IGLL1, IGHA1, and LRRC8A were key genes." (PMID 38388382, 2024).
Hepatic fibrosis (2 papers, 2017 to 2025). The presence of excessive fibrous connective tissue in the liver. "Furthermore, IGHA1 and 2 carried high levels of A2F bisect glycan and its precursors, and the levels correlated strongly with liver fibrosis." (PMID 39849179, 2025).
lymphoma (2 papers, 2019 to 2024). A malignant (clonal) proliferation of B- lymphocytes or T- lymphocytes which involves the lymph nodes, bone marrow and/or extranodal sites. "The only exception was a DH lymphoma with mBL signature presenting in the tonsil of a 75-year-old patient that displayed an IGH-MYC fusion with a breakpoint in the IGHA1 switch region (case 4182605)." (PMID 30926794, 2019).
ulcerative colitis (2 papers, 2022 to 2023). An inflammatory bowel disease involving the mucosal surface of the large intestine and rectum. "The component of immune cells in the colon has been regulated by IGHA1 during ulcerative colitis." (PMID 37763280, 2023).
Achalasia (1 paper, 2016). A disorder of esophageal motility characterized by the inability of the lower esophageal sphincter to relax during swallowing and by inadequate or lacking peristalsis in the lower half of the body of the esophagus. "Genes implicated in innate defense against pathogens, like CXCL17, IGHA1, and IGHA2, were down-regulated in patients with achalasia." (PMID 27511445, 2016).
colon cancer (1 paper, 2017). "About colon cancer data set DIEXF, GUCA2A, CA7, and IGHA1 key genes with the accuracy of 87.39 and precision of 85.45 were selected." (PMID 29563929, 2017).
invasive carcinoma (1 paper, 2023). A carcinoma that is not confined to the epithelium, and has spread to the surrounding stroma. "FGF2 and IGHA1 had significant (p < 0.05) downregulation in invasive carcinoma compared with normal breast tissues." (PMID 37445737, 2023).
ischemic stroke (1 paper, 2023). A stroke disorder caused by obstruction of blood flow to the brain, due to thrombotic (local blood clot formation) or embolic (due to a blood clot or other material traveling from another site) event. "In addition, IGHA1, LRG1, IGHV3-64D, and CP are upregulated in patients with ischemic stroke and downregulated after rehabilitation, which may be used as biomarkers to monitor neurological impairment and recovery after stroke." (PMID 36959823, 2023).
mental disorder (1 paper, 2017). A disease that has its basis in the disruption of mental process. "Immunoglobulin heavy constant alpha (IGHA1) is a major immunoglobulin, here, the serum level of this protein changes significantly in the patients with OCD; however, it is not reported as a candidate protein in other mental disorders." (PMID 29158881, 2017).
osteosarcoma (1 paper, 2022). A usually aggressive malignant bone-forming mesenchymal neoplasm, predominantly affecting adolescents and young adults. "In the TARGET‐osteosarcoma dataset, we noticed that patients with higher IGHA1_B gene signature score were associated with better EFS and OS, suggesting tumour suppressive roles of IGHA1_B cells in osteosarcoma patients." (PMID 36305631, 2022). "Naïve IGHD+ B and immune regulatory IGHA1+ B cells were largely identified in MPE, whereas bone metabolism‐related CLEC11A+ B cells were significantly enriched in osteosarcoma PT." (PMID 36305631, 2022).
renal carcinoma (1 paper, 2025). A carcinoma arising from the epithelium of the renal parenchyma or the renal pelvis. "Additionally, in renal cancer, high IGHA1/IGHG1 ratios were linked to worse survival." (PMID 40990023, 2025). "Most surprisingly, the high ratio of IGHA1 to IGHG1 very strongly correlated with prolonged survival in renal cancer." (PMID 40990023, 2025).
sarcoma (1 paper, 2023). A usually aggressive malignant neoplasm of the soft tissue or bone. "Multiple genes were downregulated (p < 0.05) in sarcoma tumors, including HSP90AB1, IGHA1, INSM1, IRF5, MAP2K2, and SEH1L." (PMID 37445737, 2023).
Stroke (1 paper, 2023). Sudden impairment of blood flow to a part of the brain due to occlusion or rupture of an artery to the brain. "By the PRM validation, IGHA1, LRG1, IGHV3-64D, and CP may be biomarkers of neurological recovery after stroke." (PMID 36959823, 2023).
Warthin tumor (1 paper, 2024). An adenoma characterized by an oncocytic, often papillary, epithelial component, dense lymphoid stroma, and cystic spaces. "On the other hand, the protein network detected in Warthin’s tumors (e.g., IGHG1, IGKC, IGHA1, and S100A9) was associated with immunological and inflammatory diseases." (PMID 39684268, 2024).
infection (59 papers, 2007 to 2025). The state of being infected such as from the introduction of a foreign agent such as serum, vaccine, antigenic substance or organism. "IGHA1 is produced by B lymphocytes and is involved in humoral immunity, which may serve both to defend against localized infection and prevent the access of foreign antigens to the immune system." (PMID 35068329, 2022). "IGHA1 and IGHA2 are protein-coding genes that may serve both to defend against local infection and to prevent access of foreign antigens to the immune system." (PMID 27511445, 2016). "Immunoglobulin heavy constant alpha 1 (IGHA1) is the constant region of the immunoglobulin heavy chain of IgA, which plays an important role in immune defenses against infection and excludes foreign antigens." (PMID 40161722, 2025).
tumor (36 papers, 2010 to 2025). "As expected, only the secretory spliced form was detected in plasmablasts in the tumor from the same patient, and most were assigned IGHA1 isotypes." (PMID 31311926, 2019). "B cells from COPD and cancer shared biological functions, and tumor‐infiltrating B cells overexpressed genes (IGHG1‐4, IGKC, IGHA1) consistent with COPD." (PMID 41377765, 2025). "While showing signs of tumor adaptation, the margin retained normal tissue characteristics, with downregulation of genes involved in iron accumulation, detoxification, and immune response (FTL, SERPINA3, IGHA1)." (PMID 40431665, 2025). "Our further research suggested that WAKMAR2 is crucial in regulating the tumour microenvironment and may function by regulating immune-related genes, including IL27RA, RAC2, FABP7, IGLV1-51, IGHA1, and IGHD." (PMID 34321580, 2021). "By contrast, both IGHA1 and MUC1, known O‐linked glycoproteins, showed no detectable change between normal and tumor tissue indicating that the changes in O‐linked glycoproteins observed in tumor tissue are highly selective." (PMID 30459171, 2018). "We assessed the correlation between immune infiltration and the expression of 25 genes (IGHA1 is not available, and FAT is named FAT1) in TCGA-BRCA patients (n = 1100) using Tumor Immune Estimation Resource (TIMER) 2.0." (PMID 37445737, 2023).
cancer (13 papers, 2013 to 2025). A tumor composed of atypical neoplastic, often pleomorphic cells that invade other tissues. "Single‐cell sequencing revealed these cells express IGHG family and IGHA1—immunoglobulins linked to cancer progression and metastasis." (PMID 41377765, 2025). "The overexpression and copy number amplification of ANKRD22 and LIPM in early cancer, and overexpression, mutation, and copy number amplification of IGHA1 in early cancer may all promote early metastasis." (PMID 37152984, 2023). "Cancer‐associated genes (VIM, IGHG1‐4, IGKC, IGHA1) were upregulated, and CPCAT data revealed correlations of IREB2 with IGHG1 and VIM, and CD27 with IGHG1." (PMID 41377765, 2025). "In another study, it was revealed that the expression of IGHA1 is increased in epithelium-derived cancer cells." (PMID 34588521, 2021).
IGHA1 also shares sentences with these, for which no sentence is quoted: IgA nephropathy (221 papers); kidney disease (54); nephritis (35); IgA vasculitis (32); glomerulonephritis (20); glomerular diseases (16); chronic kidney disease (15); Hematuria (15); glomerulosclerosis (12); influenza (11); Nephropathy (11); vasculitis (11); lupus nephritis (10); rheumatoid arthritis (8); kidney failure (7); viral infections (7); Crohn disease (6); Glomerular sclerosis (5); membranous nephropathy (5); multiple myeloma (5); primary Sjögren’s syndrome (5); systemic lupus erythematosus (5); asthma (4); cholera (4); Hypertension (4); inflammation (4); meningitis (4); minimal change disease (4); renal failure (4); Alport syndrome (3).
A further 94 diseases each share a sentence with IGHA1 in 3 papers or fewer.